INS (insulin)
Diseases named in the same sentence as INS in open-access papers (continued):
Sharing a sentence is not in itself a finding about the gene and the disease.
diabetes (continued). "Diabetes mellitus (DM) is a common metabolic disease resulting from a defect in insulin secretion, a defect in insulin action or a combination of both." (PMID 32652980, 2020). "It is also important to emphasize that associations between insulin and SUs and mortality, is not necessarily cause and effect, rather it could be a reflection on the overall progression of the diabetes in individuals requiring these agents." (PMID 32256448, 2020). "Diabetes mellitus (DM), characterized by hyperglycemia and deficits in insulin secretion or action, is one of the major chronic metabolic disorders." (PMID 32188147, 2020). "Diabetes mellitus is a complex metabolic disorder characterized by hyperglycemia, pancreatic beta (β) cells dysfunction, and abnormal lipid profile that result from metabolic deregulations, impaired insulin secretion and action, and inappropriate consumption of glucose." (PMID 32256963, 2020). "Corroborating the toxicity of these aggregates in diabetes, the IAPP allele S20G, which raises IAPP aggregation propensity, has been associated with premature onset diabetes and has accelerated the decline of endogenous insulin secretion when compared to non-S20G T2DM individuals." (PMID 32265649, 2020). "Diabetes mellitus (DM) is an endocrine and metabolic disorder characterized by impaired insulin secretion and increased blood glucose level." (PMID 32879632, 2020). "Moreover, we confirmed that renal function does not improve algorithm performance in adults, and this may reflect the growing variety of non-insulin agents available for people with diabetes and impaired renal function." (PMID 32093635, 2020). "Furthermore, neither of these studies tested diabetes risk variables such as fasting insulin or HOMA-IR." (PMID 32131847, 2020). "Diabetes became manifest despite treatment in case 1 and 3, while in case 2, who was already known with insulin-dependent diabetes at baseline, glucose and HbA1c levels improved and insulin doses could be reduced." (PMID 32334607, 2020). "Importantly, GLP1RA therapy facilitated significant insulin dose reduction, altogether leading to resolution or at least marked improvement in severity and frequency of previously reported hypoglycemic events while diabetes remained well controlled." (PMID 32095510, 2020). "Poor diabetes control in East Africa may be also related to problems with insulin." (PMID 32704558, 2020). "Further, given the role of healthcare professionals, such as pharmacists, in managing diabetes collaboratively with patients, it is important to further elucidate whether switching to patch-like basal-bolus insulin delivery devices provides benefits to patients in real-world settings." (PMID 33202616, 2020). "Several clinical trials have addressed the therapeutic strategy of adding dipeptidyl peptidase 4 (DPP-4) inhibitors to the treatment of type 2 diabetes mellitus (DM) inadequately controlled by insulin therapy." (PMID 33224988, 2020). "Nanocapsules incorporating chitosan, insulin, and the GOx enzyme were formulated as monodispersed microgels which could swell in a hypoglycemic environment by the protonation of chitosan, thereby releasing insulin for the treatment of diabetes." (PMID 32580366, 2020). "The diet composition of athletes with diabetes must contain other essential macronutrients such as proteins and fats which, if taken correctly, may slightly contribute to the increase in postprandial blood glucose levels and to the need for prandial insulin." (PMID 33467298, 2020). "Indeed, in the DIGAMI study (﻿Diabetes Mellitus Insulin-Glucose Infusion in Acute Myocardial Infarction), insulin infusion post-acute myocardial infarction, followed by multi-dose subcutaneous insulin administration, decreased mortality rate in patients with diabetes." (PMID 32508651, 2020).
diabetes (continued). "Furthermore, FKBPL levels were negatively correlated with characteristic metabolic parameters for T2D, glucose and HbA1c, and positively correlated with C-peptide (reflecting endogenous insulin secretion) and the duration of diabetes, in the FIELD study samples." (PMID 33303872, 2020). "In mouse models of obesity/diabetes, increased glucose intolerance, reduced serum insulin levels, and reduced tissue glucose uptake after chemerin administration were observed, despite the fact that some studies suggested that chemerin is necessary for the proper insulin production by the pancreas." (PMID 33081064, 2020). "It was hypothesised that eating disorder behaviours would be higher in adolescents reporting diabetes compared to those without, and that insulin restriction would be associated with greater disordered eating behaviours." (PMID 32128205, 2020). "The shape of the pancreas may also influence (or be correlated with factors that influence) diabetes remission following very-low-energy diets, such that improvements in early insulin secretion are greater in individuals with regularly rather than irregularly shaped pancreases." (PMID 32002573, 2020). "Insulin is essential for regulating a large range of intracellular metabolic processes; however, chronic high levels of insulin resulting from excessive nutrient intake may also be involved in the pathogenesis of metabolic diseases like obesity, diabetes, and NAFLD." (PMID 32350271, 2020). "As muscle is one of the principal target of insulin action and, consequently, is a major site of glucose disposal, and since muscle mass and function progressively decrease with age, the physiopathological link between sarcopenia, aging, and diabetes is so far established." (PMID 32316601, 2020). "We identified seven criteria for diabetes progression: ‘Initiation of insulin’, ‘Initiation of oral antidiabetic drug’, ‘treatment intensification’, ‘antidiabetic therapy failure’, ‘glycaemic deterioration’, ‘decline in beta‐cell function’ and ‘change in insulin dose’." (PMID 32318630, 2020). "Furthermore, various studies have proven the superiority of insulin pump therapy across all age groups of patients with diabetes regarding glycemic control, duration of normoglycemia, incidence of severe hypoglycemia, quality of life, and lower rate of long-term complications." (PMID 33334003, 2020). "Diabetes mellitus (DM) is a metabolic disorder characterized by hyperglycemia which results from insufficient secretion and/or reduced insulin action in peripheral tissues." (PMID 32182246, 2020). "In addition, given the fact that Germany is a country with a high use of insulin per capita, the results of this study may increase the awareness to minimize the incidence of hypoglycemic episodes in insulin-treated diabetes patients." (PMID 33292431, 2020). "Hwang and Bugeja (2000), found that one of the major difficulties reported by homeless people were difficulties in prioritising their diabetes conditions over other problems they may be experiencing, accessing and securing insulin needles and syringes, obtaining medications and exercising." (PMID 33095271, 2020). "Diabetes mellitus (DM) comprises a group of metabolic disorders characterized by hyperglycemia, which is due to the impairment of insulin secretion and/or action." (PMID 32635449, 2020). "In this study, we aimed to study the effect of insulin on cell activation and airway responsiveness in patients with diabetes mellitus (DM)." (PMID 33145961, 2020). "In addition to already documented gastrointestinal health-promoting properties and risk of cancer reduction abilities, raphia palm wine recently reported as a modulator of glucose homeostasis in a rat model of diabetes by enhancing insulin secretion and inhibiting redox imbalance." (PMID 32015447, 2020).
diabetes (continued). "Diabetes mellitus is a metabolic disorder caused by insufficient or no insulin production by the pancreas or by an impaired response to insulin, which can lead to bone loss, referred to clinically as secondary osteoporosis, resulting in an increased risk of bone fractures." (PMID 32570976, 2020). "Diabetes mellitus (DM) is a metabolic disease, in which the serum glucose level is elevated due to a problem in insulin synthesis and/or its function." (PMID 32133264, 2020). "With this high degree of inertia to employ insulin by the PCPs, patients who are not optimally controlled on oral medications would therefore remain in chronic hyperglycemia which is an established risk factor for many of the diabetes complications." (PMID 32611395, 2020). "Diabetes mellitus (DM) is a life-threatening metabolic disorder characterized by chronic hyperglycemia resulting from defects in insulin secretion, insulin action, or both." (PMID 32586304, 2020). "Uncontrolled diabetes (vs. controlled) is associated with lower EF performance, and the decline in EF is largely caused by hyperglycemia [fasting glucose and glycated hemoglobin (HbA1C)], but not insulin resistance." (PMID 32973635, 2020). "Diabetes mellitus (DM) is a hyperglycemic condition induced either by a failure to secrete insulin due to dysfunctional β-cells (type I) or insulin resistance (type II)." (PMID 32106662, 2020). "For example, in the context of liver disease to assess whether Treg cell infusion could improve liver function tests (liver enzymes—alanine transaminase and aspartate transaminase, bilirubin) and in the context of diabetes (insulin requirement and c-peptide level improvement)." (PMID 33072105, 2020). "Furthermore, it has been shown that insulin, a medicine for treating hyperglycemia or diabetes, can attenuate ACE2 expression, suggesting that well-controlled glycemia may reduce the risk of COVID-19 infection via decreasing the cellular levels of ACE2." (PMID 33002109, 2020). "The most common type of diabetes mellitus (DM) is T2D, which is illustrated by diminished secretion of insulin, insulin resistance, and β-cell dysfunction." (PMID 32695286, 2020). "The pooled effect size for AD in relation to obesity and diabetes was calculated at 1.59 and 1.54 in longitudinal epidemiological studies of body mass, metabolic syndrome (dyslipidemia, hypertension, abdominal obesity, and insulin resistance), diabetes, and glucose and insulin levels." (PMID 32899357, 2020). "Finally, a previous study of adults without diabetes showed an inverse association of log insulin (and log-HOMA-IR) with SDNN, RMSSD, log LF, and log HF using 24-h electrocardiography recordings (n = 94)." (PMID 32393179, 2020). "Diabetes is a globally widespread disease characterized by hyperglycemia due to autoimmune destruction of insulin (INS)-producing β cells (type 1 diabetes; T1D) or to extensive β cell exhaustion and depletion after hypersecretion of INS to overcome INS resistance (type 2 diabetes; T2D)." (PMID 33198821, 2020). "Thus, a SARS-CoV-2/ACE2-mediated dysregulation of insulin signaling could further aggravate symptoms in diabetics." (PMID 33328942, 2020). "For example, while high intensity interval training has been observed to increase aerobic capacity in both men and women, its ability to enhance insulin sensitivity appears to be blunted in women, which may have implications for prediabetes and diabetes but remains to be studied." (PMID 32626778, 2020). "At the same time, they frequently have advanced technologies (e.g. insulin pumps and continuous or flash glucose monitoring systems), which provide in-depth data, able to share on-line with health care professionals, allowing detailed analysis and advice for diabetes care at a distance." (PMID 32891126, 2020).
diabetes (continued). "However, this study also highlighted that the intrasubject variability concerning the total insulin exposure was 26% for the inhaled group, indicating the consistent inhalation techniques could play a significant role in the treatment of diabetes." (PMID 32785196, 2020). "Diabetes mellitus (DM) is a progressive and chronic metabolic disorder characterized by hyperglycemia arising from impaired insulin levels, insulin sensitivity, and/or insulin activity." (PMID 32824240, 2020). "For example, diabetes and insulin resistance are associated with increased fracture risk, but glucose-clamp studies infusing insulin across the physiological range showed no change in bone formation or resorption, suggesting insulin per se does not directly impact bone metabolism." (PMID 32016644, 2020). "This may be due to the fact that these variables are not causative of diabetes, but they rather share a common pathophysiology, probably linked to the loss of insulin sensitivity." (PMID 32066839, 2020). "Besides the role in insulin metabolism, the lower doses of ZnO NPs might have a protective effect on diabetes rat sperm, owing to their antioxidant properties." (PMID 32069903, 2020). "Diabetes mellitus (DM), more simply called diabetes, is a group of metabolic diseases characterised by hyperglycaemia resulting from defects in insulin secretion, insulin action, or both." (PMID 32775461, 2020). "Therefore, insulin sensitivity is improved at lower temperatures, which may explain the adverse effects of elevated temperature on diabetes." (PMID 33134393, 2020). "One patient with type VI (patient 11) developed diabetes mellitus (DM) type 1 at the age of 4 and was treated with insulin." (PMID 32414085, 2020). "This impairment in insulin secretion might be explained by insufficient β-cell mass, and/or functional defects within the β-cells themselves, in patients with T2DM and individuals at risk for diabetes." (PMID 33096658, 2020). "The biological mechanism by which apical periodontitis could alter the metabolic control of diabetes, increasing HbA1c levels, would be related to the induction of a systemic inflammatory status, contributing to increased insulin resistance and poor glycaemic control." (PMID 32079175, 2020). "Interestingly, mutating the tyrosine to alanine at position 16 of the insulin B chain prevented antigen recognition by pathogenic insulin-reactive CD4+ and CD8+ T cells and protected NOD mice from developing diabetes, demonstrating the importance of this B chain region of insulin in T1D development." (PMID 33262765, 2020). "Diabetes mellitus (DM) is a metabolic disease commonly observed in the clinic and is characterized by hyperglycemia due to impaired insulin secretion, insulin resistance, or both, resulting in impaired metabolism of sugars, lipids, and proteins." (PMID 32792939, 2020). "Traditionally, both major forms of diabetes have been viewed as distinct: T1D develops as a result of selective destruction of pancreatic β cells by the immune system, while T2D develops secondary to insufficient insulin secretion in the context of insulin resistance in peripheral tissues." (PMID 32736653, 2020). "Moreover, long-term subcutaneous injections of insulin due to diabetes mellitus can give rise to local insulin-derived amyloid deposits, which is of course important to be aware of when performing an abdominal fat pad biopsy for amyloid diagnosis on a patient with insulin treatment." (PMID 33032630, 2020). "In different models of diabetes in vivo, the ethyl acetate extracts prepared from aerial parts and fruits of Physalys alkekengi increased the uptake of glucose in HepG2 cells and reduced the glycemia, cholesterol, triglyceride and glycated protein levels and increased insulin sensitivity." (PMID 32824505, 2020).
diabetes (continued). "Therefore, we recommend that the Ministry of Health of Saudi Arabia takes appropriate steps to increase the number of qualified physicians to deal with patients on insulin pump therapy, particularly considering the constantly growing prevalence of diabetes cases in Saudi Arabia every year." (PMID 33334003, 2020). "Therefore, both in vitro and in vivo results suggest that irINS-Tf could achieve the same or better glycemic control with less dose than native INS in treating INS-resistant diabetes." (PMID 32382087, 2020). "Diabetes mellitus (DM) is a heterogeneous metabolic disease characterized by chronic hyperglycemia resulting from defects in insulin secretion, insulin action, or both." (PMID 33042026, 2020). "Diabetes mellitus (DM) is a group of metabolic diseases affecting the metabolism of carbohydrates, lipids and proteins, with hyperglycemia, as a result of a deficiency in insulin secretion, lack of insulin action or both." (PMID 33154799, 2020). "Infection, intensive care unit admission, lower body mass index, insulin regimen and nutritional therapy (enteral feeding and nothing-per-mouth (NPO)) were correlated with an elevated risk of having hypoglycemia in hospitalized patients with type 2 diabetes mellitus." (PMID 32133264, 2020). "Diabetes mellitus (DM), a metabolic disorder of various etiologies, is characterised by chronic hyperglycaemia and disturbances in insulin secretion or its activity, or both." (PMID 33008059, 2020). "Different types of diabetes patients did not showsignificant differences in risk perception to all drugs used in the control ofdiabetes, and overall had a higher risk perception for insulin as compared withoral hypoglycaemic agents." (PMID 35173953, 2020). "In general, systemic administration of recombinant human IGF-1 may reduce the levels of insulin and glucose in diabetes patients with reduced response to insulin, which indicates that IGF-1 is capable of increasing insulin sensitivity and has broad effects on IR and hyperglycemia." (PMID 33905470, 2020). "Pharmacological treatment of diabetes includes insulin and hypoglycemic and anti-hyperglycemic drugs, which will depend on the stage and type of DM." (PMID 32774865, 2020). "The present study aimed to determine whether we could similarly reverse diabetes in the non-obese diabetic (NOD) mouse using an adeno-associated viral vector (AAV) to deliver INS-FUR ± the β-TF Pdx1 to the livers of diabetic mice." (PMID 33023100, 2020). "Thus, elucidation of the mechanisms involved in insulin regulation and β-cells dysfunction may open additional avenues for the development of novel therapeutic strategies for the treatment of diabetes." (PMID 32182790, 2020). "Despite the clinical benefits of moderate glycemic control in the perioperative setting, insulin use in patients without diabetes was associated with worse clinical outcomes compared to patients (both with and without diabetes) who did not receive insulin in a risk-adjusted model." (PMID 33118731, 2020). "Diabetes mellitus (DM) is a chronic metabolic disorder commonly characterized by abnormally high blood glucose levels, resulting from defects in insulin production or insulin resistance, or both." (PMID 33274235, 2020). "Of 54 participants with diabetes, 26 (48%) reported a previous diagnosis of diabetes, 18 of whom (69%) reported regular diabetes follow-up visits at a health centre or with a doctor, whilst 24/26 (92%) reported currently taking diabetes medication (21 metformin or metformin + insulin)." (PMID 32139742, 2020). "In contrast to energy metabolism in cardiac hypertrophy, the energy metabolism in diabetes and obesity-induced cardiac remodeling is characterized by increased fatty acid intake and oxidation but decreased glucose oxidation because of impaired insulin signaling." (PMID 33328993, 2020). "But when it came to the insulin for the diabetes, I felt that I couldn’t trust them." (PMID 31825747, 2020).